TK2 (thymidine kinase 2)
Diseases named in the same sentence as TK2 in open-access papers (continued):
Sharing a sentence is not in itself a finding about the gene and the disease.
lung adenocarcinoma (1 paper, 2019). A carcinoma that arises from the lung and is characterized by the presence of malignant glandular epithelial cells. "Our data indicate that DGUOK is overexpressed in lung adenocarcinoma patients and the expression levels of DGUOK, but not TK2, strongly correlate with the survival of lung adenocarcinoma patients." (PMID 31633874, 2019).
non-small cell lung carcinoma (1 paper, 2015). A group of at least three distinct histological types of lung cancer, including non-small cell squamous cell carcinoma, adenocarcinoma, and large cell carcinoma. "None of these effects (sensitization to gemcitabine or mitochondrial toxicity) were seen in A549 non-small cell lung cancer cells with low basal TK2 expression (7% of that in MCF7 and 25% of that in HeLa cells)." (PMID 26087398, 2015).
Skeletal myopathy (1 paper, 2020). "The 5′-phosphoramidate of ATI-2173 generates the 5′-monophosphate bypassing the first phosphorylation step of clevudine, which uses the TK2 enzyme and may be responsible for the reversible skeletal myopathy seen in chronically dosed patients." (PMID 32540975, 2020).
myopathy (20 papers, 2013 to 2026). A disease of the muscle in which the muscle fibers do not function properly. "TK2 deficiency (TK2d) is a rare mitochondrial disorder that manifests predominantly as a progressive myopathy with a broad spectrum of severity and age of onset." (PMID 35286480, 2022). "Mutations are also found in the TK2 gene encoding thymidine kinase 2, which leads to early and severe myopathy with depletion in skeletal muscle." (PMID 34680481, 2021). "Autosomal recessive TK2 mutations cause a spectrum of disease from infantile onset to adult onset manifesting primarily as myopathy." (PMID 29602790, 2018). "The demonstration of severe mtDNA depletion prompted screening of genes associated with mtDNA depletion myopathy (TK2 and RRM2B) in subjects 1 and 2 prior to WES." (PMID 27693233, 2016). "The phenotype in patients seems to correspond to the severity of the TK2 deficiency, where partial reductions of TK2 activity (14–45% of normal) lead to myopathy and severe reductions (<10% of normal) cause encephalomyophathy." (PMID 23505564, 2013). "Consistently, we found extensive overlap between the DELE1 mt-ISR signature in the skeletal muscle of the IMMD mouse model of myopathy and genes upregulated in three cohorts of patients with MM, which included patients with mutations in Twinkle, TK2, and mtDNA." (PMID 39379554, 2024). "Recessive mutations in the TK2 gene are responsible for a syndrome of mitochondrial depletion/multiple deletions in mtDNA that can manifest at any age, most often as a pure progressive myopathy." (PMID 35286480, 2022). "A second study described severe myopathy and mtDNA depletion in skeletal muscle, brain demyelination, liver steatosis and hypertrophic cardiomyopathy in a 22-month-old girl harbouring two missense mutations in the TK2 gene." (PMID 34070501, 2021). "In summary, our study shows that late-onset patients with mitochondrial TK2 deficiency have a consistent and recognizable clinical phenotype, characterized by a progressive myopathy with predominant facial and axial neck flexor weakness, and respiratory involvement, often associated to CPEO." (PMID 31060578, 2019). "Indeed, severe infantile myopathy, which is typical of reduced TK2 activity, has been reported for a subject who harbors a homozygous nonsense mutation in exon 10, which is exclusively included in the canonical TK2 ORF." (PMID 35084690, 2023). "Treatment-related marked improvements of mtDNA levels and biochemical defects in muscle, which is the most affected tissue in TK2 mutant patients, suggest that dCMP/dTMP might be more efficacious in patients with myopathy due to TK2 deficiency than in Tk2−/− mice with severe CNS involvement." (PMID 24968719, 2014).
mitochondrial disease (8 papers, 2014 to 2025). "Early or childhood onset of Thymidine Kinase 2 Deficiency, a mitochondrial disease, demonstrated 30‐fold higher GDF15 levels compared to controls, with improvement in clinical outcomes and decreases in GDF15 after treatment with oral deoxynucleosides." (PMID 40019842, 2025). "Inflammatory features have scarcely been reported in mitochondrial diseases; with these findings, we confirmed the previous inflammatory features detected by our group in TK2-deficient patients using a transcriptomic analysis." (PMID 36232299, 2022). "A growing number of mitochondrial diseases with mtDNA instability have been linked to mitochondrial deoxynucleotide pool imbalance, including deficiencies of TK2, dGK, RRM2B or TYMP." (PMID 29602790, 2018). "Mitochondrial diseases and, in particular, TK2 deficiency are often associated with local (skeletal muscle) inflammatory responses which may be related to muscle cell damage or necrosis." (PMID 32572108, 2020). "In addition, we demonstrated that GDF-15 outperformed other diagnostic biomarkers for mitochondrial diseases and postulated that it may also serve to monitor response to treatment based on preliminary data of one patient with TK2 deficiency that was treated with deoxynucleotides replacement therapy." (PMID 32572108, 2020). "Also, patients with mitochondrial diseases affecting muscle argue against this (TK2, SUCLA2, SUCLG1, RRM2B, DGUOK, and TYMP)." (PMID 30538797, 2018). "This reflects the differences in the pathology of both forms of mitochondrial disease, muscle biopsies from patients with MDEL generally do not show proliferation of connective tissue or generation and in fact CK levels are normal whereas they are elevated in MDS patients with TK2 mutations." (PMID 24484525, 2014).
cancer (7 papers, 2013 to 2025). A tumor composed of atypical neoplastic, often pleomorphic cells that invade other tissues. "Genetic deficiency for either of the two mt deoxynucleoside kinases, TK2 and dGK, is associated with mtDNA depletion and severe mt diseases." (PMID 26342080, 2015). "TK2 appears to have potential as a therapeutic target in cancer treatment and as a diagnostic biomarker of relative resistance to gemcitabine in human tumors." (PMID 26087398, 2015). "Therefore, TK2 downregulation is a metabolic hallmark of pluripotency, whereas its maintenance in cancer cells is a consequence of TK1-driven nucleotide metabolism rather than a defining metabolic adaptation." (PMID 40571767, 2025). "Conversely, in cancer cells, TK2 maintains mtDNA stability and regulates reactive oxygen species, promoting metabolic flexibility and tumorigenic survival." (PMID 40571767, 2025). "As TK1 is the predominant thymidine kinase present in normal proliferating cells as well as cancer cells, the role of mitochondrial cell-cycle independent TK2 in cancer must be further investigated." (PMID 35203388, 2022). "We previously reported that TK2 has potential as a therapeutic target in treatment of human cancers if its down-regulation by antisense is combined with widely-used cytotoxic anticancer agents and antisense molecules targeting thymidylate synthase (TS)." (PMID 26087398, 2015). "We show for the first time that siRNA-mediated knockdown of TK2 sensitized TK2-expressing cancer cell lines (MCF7 and HeLa) to the anti-proliferative effects of gemcitabine in vitro." (PMID 26087398, 2015). "Viral vectors have also been engineered to deliver and encode transgenes that act as “suicide-genetic switch” for controlled lysis of target cancer cells, for example by using ganciclovir to induce cell death of tumor cells expressing a thymidine kinase (TK2) transgene." (PMID 34761104, 2021). "This is the first demonstration of a direct role for TK2 in gemcitabine resistance, or any independent role in cancer drug resistance, and further distinguishes TK2 function from that of other dTMP-producing enzymes [cytosolic TK1 and thymidylate synthase (TS)]." (PMID 26087398, 2015). "Thus, while PS cells and cancer cells share metabolic features such as dependence on glycolysis and altered mitochondrial metabolism, they significantly differ in their regulation of TK2 and TK1." (PMID 40571767, 2025). "The potential of TK1 and TK2 as anti-cancer targets in combination with other pyrimidines de novo synthesis inhibitors has only been demonstrated in vitro so that further in vivo experiments are required to fully understand the potential effect of TKs in cancer." (PMID 35203388, 2022). "In cancer cells, rapid proliferation leads to abnormal TK1 activation, reducing reliance on TK2, whereas PS cells exhibit selective TK2 downregulation as part of their metabolic transition toward glycolysis and reduced mitochondrial activity." (PMID 40571767, 2025). "The activity of both, cytosolic (TK1) and mitochondrial thymidine kinase (TK2), is upregulated by anti-cancer agents targeting thymidine synthase (TS) in the pyrimidine de novo synthesis pathways." (PMID 35203388, 2022). "siRNA knockdown of TK1 and/or TS did not sensitize cancer cells to gemcitabine indicating that, among the 3 enzymes, only TK2 is a candidate therapeutic target for combination with gemcitabine." (PMID 26087398, 2015).
tumor (7 papers, 2004 to 2021). "DNA analysis revealed two gain-of-function mutations of the c-kit gene in the relapsing tumours: an in-frame mutation in exon 11, which encodes a region in the juxtamembrane domain; and a missense point mutation in exon 17, which encodes the tyrosine kinase (TK2) domain." (PMID 15150562, 2004). "MCF7, HeLa and A549 human tumor cell lines differed with respect to basal TK2 protein and are labeled TK2HIGH (MCF7), TK2MEDIUM (HeLa) and TK2LOW (A549)." (PMID 26087398, 2015). "In that scenario, antisense-reduced TS and TK2 combined to sensitize human tumor cells to the anti-TS drug 5-FUdR." (PMID 26087398, 2015). "Overall, these data indicate that endogenous TK2 in human tumor cells can reduce the therapeutic efficacy of gemcitabine, and antisense knockdown of TK2 increases gemcitabine activity." (PMID 26087398, 2015). "At present, however, it is not clear whether FLT could reach the mitochondria to be phosphorylated by TK-2 in intact tumour cells." (PMID 18665170, 2008). "The effect was specific to TK2, as knockdown of other dTMP-producing enzymes (thymidylate synthase and TK1), alone or in combination with TK2 siRNA treatment, did not further sensitize tumor cells to gemcitabine beyond that induced by TK2 knockdown alone." (PMID 26087398, 2015). "An increase in dCK levels in human tumor cells was demonstrated for the first time in response to combined treatment with TK2 siRNA and gemcitabine (but neither treatment alone)." (PMID 26087398, 2015). "siRNA-mediated knockdown of TK2 alone did it not reduce tumor cell proliferation, nor did it sensitize cells to pemetrexed, cisplatin, or 5FUdR." (PMID 26087398, 2015). "However, TK2 and NT5C2 were not significantly upregulated in tumor tissues." (PMID 32638267, 2020).
TK2 also shares sentences with these, for which no sentence is quoted: mitochondrial neurogastrointestinal encephalomyopathy (3 papers); Pearson syndrome (2); amyotrophic lateral sclerosis (1); Ataxia (1); Barth syndrome (1); bladder cancer (1); esophageal cancer (1); facioscapulohumeral muscular dystrophy (1); Friedreich ataxia (1); gastric cancer (1); gastrointestinal stromal tumor (1); infection (1); lactic acidosis (1); Leber hereditary optic neuropathy (1); Leigh syndrome (1); lipid storage myopathy (1); liver cancer (1); metabolic disorders (1); mitochondrial DNA depletion syndrome types 1 (1); multiple sclerosis (1); myonecrosis (1); neurological disease (1); neuronal intranuclear inclusion disease (1); neuropathy (1); oculopharyngeal muscular dystrophy (1); pancreatic tumours (1); Parkinsonism (1); Pleural effusion (1); Progressive cerebellar ataxia (1); prostate carcinoma (1).
A further 3 diseases each share a sentence with TK2 in 1 paper.